IL6 (interleukin 6)
Diseases named in the same sentence as IL6 in open-access papers (continued):
Sharing a sentence is not in itself a finding about the gene and the disease.
peritonitis (continued). "In an acute model of sterile inflammation using a murine model of pristane-induced peritonitis the IFN-I signaling was responsible for monocyte recruitment and maturation during inflammation while mice deficient in TLR4, TNFα, IL-6, and IL1R failed to accumulate monocytes in the peritoneal cavity." (PMID 33995391, 2021). "Furthermore, F240B exerted in vivo anti-inflammatory activity by reducing the intraperitoneal influx of neutrophils and the levels of IL-1β, active caspase-1, IL-6 and monocyte chemoattractant protein-1 (MCP-1) in lavage fluids in a mouse model of uric acid crystal-induced peritonitis." (PMID 33424855, 2020). "However, the sample size was small (n = 46), and the potential impact of peritonitis on dialysate IL-6 levels was not separately explored." (PMID 24410736, 2014). "Furthermore, lack of a decrease in dialysate IL-6 concentrations with treatment of acute peritonitis has been shown to predict relapsing peritonitis." (PMID 24895536, 2014). "Taking into account the control group from the postoperative period, we have compared the variation of IL–6 and TNF alpha levels, determined in day 7, with the three categories of diagnostic from that particular period, namely peritonitis with or without septic complications and the control group." (PMID 21776298, 2011). "In the human NLRP3 129S6 mice in a peritonitis model, we show that BAL-0598 dose dependently blocks IL-1β release but not IL-6." (PMID 40892070, 2025). "The underlying causes might be inter-individual variation of IL-6, lack of repeated measurements and increased peritoneal concentrations could be due to mesothelial cell injury by repeated exposures to bioincompatible PDF but also secondary to peritonitis episodes." (PMID 36035388, 2022). "With careful subgroup analysis, PD effluent IL-6 and COX-2 levels significantly increased in patients with peritonitis, but decreased in those without peritonitis." (PMID 32296091, 2020). "In addition, parenteral nutrition infusion, sub-acute peritonitis, and L-NAME administration did not have a significant impact on spontaneous, Con A-stimulated, and LPS-stimulated IL-6 production." (PMID 22879994, 2012). "However, patients who had peritonitis during the follow up period had higher PD effluent IL-6 level (26.6 ± 17.4 vs 15.1 ± 12.3 pg/ml, p = 0.037) and COX-2 level (4.97 ± 6.25 vs 1.60 ± 1.53 ng/ml, p = 0.007) after one year than patients without peritonitis." (PMID 32296091, 2020).
hyperlipidemia (127 papers, 2011 to 2026). "Owing to its strong association with multiple features of lipemia and glycemia (compared with IL-6), GlycA was used as the inflammatory biomarker for the remaining analyses." (PMID 34100082, 2021). "A prominent feature of HFD-triggered hyperlipidemia is the accumulation of lipid, as well as promoting low-grade chronic inflammation associated with increased levels of mediators such as IL-1β, IL-6, and TNF-α." (PMID 32089647, 2020). "Pro-inflammatory genes (TNF-α and IL-6) were reported to be expressed at high levels and to contribute to cardiovascular diseases caused by hyperlipidemia." (PMID 30049280, 2018). "Although little is known about triglycerides and cytokine activation, it is generally accepted that hyperlipidemia is associated with activation of proinflammatory cytokines, IL-6 in particular." (PMID 28053993, 2016). "Hyperlipidaemia is associated with anti-IL-6 bDMARDs and could lead to the higher rate of discontinuation." (PMID 39698233, 2025). "Hyperlipidemia accompanied by a high IL-6 level was a predisposing factor for arrhythmia." (PMID 38540106, 2024). "Besides ischemia-reperfusion injury and alloimmunity, hyperlipidemia was recently identified as a driver of IL-6 release in transplantation, causing Treg dysfunction and accelerated allograft rejection." (PMID 38830846, 2024). "Research has revealed that hyperlipidemia level is highly connected with m6A-SNPs and FTO-associated inflammatory factor IL-1β, IL-6, and LPS which induce hyperlipidemia may be the factors in the development of chronic heart disease." (PMID 36157445, 2022). "Hyperlipidemia causes adipocyte hypertrophy and fat accumulation in extra-adipose tissues such as liver and muscle tissues, leading to increased oxidative stress and release of cytokines, such as TNFα, interleukin (IL)-6, and IL-1β." (PMID 33922045, 2021). "The author’s previous findings had shown that serum and gingival crevicular fluid (GCF) proinflammatory cytokines such as TNF-α, IL-1b, and IL-6 levels may play an important role in association with a periodontal disease and hyperlipidemia." (PMID 26666260, 2015). "Indeed, the IL-6 receptor-inhibiting monoclonal antibody tocilizumab has resulted in increased weight gain and hyperlipidemia in humans, and there are analogous signaling and metabolic phenotypes associated with ablation of IL-1 and IL-6." (PMID 23921145, 2013). "Experimental studies indicate that asprosin can trigger proinflammatory responses in THP-1 macrophages, increasing secretion of TNF-α, IL-1β, IL-6, IL-8, and IL-12, and promotes hyperlipidemia-induced endothelial inflammation via NF-κB signaling." (PMID 41286678, 2025). "In hyperlipidemia, IL‐1β, IL‐6, IL‐8, and IL‐10 still had significant differences between the SAP group and non‐SAP group (p < .05), while IL‐5, IL‐17, TNF‐α had no statistical differences between the two groups." (PMID 38411379, 2024). "Hyperlipidemia, linked to systemic inflammation, activates the NF-κB pathway, increasing pro-inflammatory cytokines like TNF-α and IL-6." (PMID 39768728, 2024). "Biochemical examinations showed that YL significantly reduced the levels of TC, TG, LDL-c, Il6, Tnf-α, and Vegfa in hyperlipidemia mice (p < 0.01)." (PMID 37964876, 2023). "This can largely be associated with hyperlipidemia-induced chronic low-grade activation of Nuclear-Factor Kappa Beta (NF-κB) followed by canonical activation of proinflammatory factors TNF-α and IL-6." (PMID 36381991, 2022). "Unsurprising, the expression of inflammatory markers consistent with hyperlipidemia (IL-1β, IL-6, COX-2), was found at higher amounts in full-thickness tears compared to partial-thickness tears." (PMID 36381991, 2022). "PBMC from patients with hyperlipidemia, when treated in vitro with recombinant IL‐38, reduced gene expression and protein secretion of IL‐6, IL‐1β, and CRP." (PMID 33125159, 2021).
hyperlipidemia (continued). "This showed that XOS increased the level of anti-inflammatory factor IL-10 and reduced the levels of pro-inflammatory factors TNF-α, IFN-γ, and IL-6 in the serum, thus exerting a regulatory effect on the blood lipid levels of mice with hyperlipidemia." (PMID 34880767, 2021). "Even more so, a prior study found that miR-155-5p amplified the expression of IL-6 in thyroid follicle cells and also increased the IL-6 expression in hyperlipidemia and patients with familial hypercholesterolemia." (PMID 33718596, 2021). "Intriguingly, cytokines, including IL-6 and IL-8, are significantly increased in obese patients 35,36 and are used as markers that are correlated with hyperlipidemia." (PMID 32641980, 2020). "It was suggested that TUG1 promoted hyperlipidemia and inflammatory cytokines such as IL-6 and TNF-α by sponging miR-133a, which targeted the fibroblast growth factor 1 (FGF1) in ox-LDL-treated RAW264.7 cells." (PMID 32082313, 2020). "For instance, rhizoma polygonati polysaccharide from Polygonatum sibiricum and resveratrol from Reynoutria japonica improved serum lipids in hyperlipidemia-mediated AS mice and attenuated IL-6-p-STAT3 signaling." (PMID 30713570, 2019). "Pro-inflammatory genes (TNF-α and IL-6) have been reported to be expressed at high levels and contribute to cardiac damage in hyperlipidemia." (PMID 30526612, 2018). "Pro-inflammatory genes (TNF-α and IL-6) have been reported to be expressed at high levels and contribute to kidney injury in hyperlipidemia." (PMID 30049280, 2018). "The presence of hyperlipidemia further increased the presence of IL-1 β, IL-6 and TNF in the SM in the OA-HFD group in comparison to the OA group." (PMID 29191221, 2017). "In the present study, XZK was shown to reduce the serum expression levels of TNF-α and IL-6 in the hyperlipidemia rat model." (PMID 25371725, 2014). "The experimental hyperlipidemia induced by poloxamer 407 decreased renal I/R injury, which was mediated by reduced renal IL-6 production after the insult." (PMID 24739487, 2014). "Conclusively, sustained delivery of IL-1Ra loaded in PF127 gel showed the ability to prevent hyperinsulinaemia, hyperlipidemia and elevated levels of IL-6 in GK rats." (PMID 23409091, 2013). "Interestingly, hyperlipidemia using model mice is also involved in the higher expression of inflammatory cytokines such as IL-6 and TNF-α and alveolar bone loss, and therefore, hyperlipidemia would be a risk factor of inflammation in oral cavity." (PMID 41590174, 2026). "Statins, widely used for hyperlipidemia, possess anti-inflammatory properties that may attenuate IL-6 and IL-8 production." (PMID 41126323, 2025). "Additionally, excessive fat deposition in individuals with hyperlipidemia can increase the autoinflammatory response and promote the overexpression of inflammatory factors, such as IL-6 and MCP-1, potentially contributing to TN formation." (PMID 38889391, 2024). "Also, statins, which are used as first-line drugs for hyperlipidemia management, tend to decrease inflammation by decreasing the expression of interleukin-6, which is accountable for most of the adverse events in TTS patients." (PMID 37755166, 2023). "Formerly, data suggested that inflammatory cytokines (TNFα and IL-6) may have a suppressive effect on SDF-1 in male patients with hyperlipidemia." (PMID 37894988, 2023). "In addition, exercise reduced the hyperlipidemia-induced increase in the expression of inflammatory signals, including IL-1β, IL-6, and IL-18, in kidney tissue." (PMID 37277452, 2023). "In addition, LHD treatment improved cardiac function, reduced hyperlipidemia-induced inflammatory infiltration in cardiomyocytes and suppressed the release of interleukin-6 (IL-6) and tumor necrosis factor-α (TNF-α)." (PMID 34881240, 2021). "This suggests that hyperlipidemia-associated CRC metastasis may be caused by production of cytokines, such as IL-6 and IL-8." (PMID 32641980, 2020).
hyperlipidemia (continued). "Furthermore, DT administration to VSMCs derived from SM22α-DTR mice causes release of IL-6, MCP-1 and GM-CSF in culture, and in the presence of hyperlipidemia, increases serum levels of TNF-α and IL-6 in vivo." (PMID 32627119, 2020). "However, TUG1 promoted hyperlipidemia and inflammatory cytokines such as IL-6 and TNF-α via sponging miR-133a." (PMID 32082313, 2020). "From the point of view of inflammation, pro-inflammatory genes Tumor Necrosis Factor-α (TNF-α) and Interleukin-6 (IL-6) have been reported to be expressed at high levels and contribute to cardiac damage in hyperlipidemia, in addition to canonical inflammatory markers, such as IL-18 and IL-1β." (PMID 31635164, 2019). "A previous study indicated that IL-6 levels were associated with age but not with CV risk factors (assessed by BMI, blood pressure or lipidemia) in a 20-84 year old healthy population." (PMID 24244750, 2013). "The hyperglycemic state and hyperlipidemia in turn activate glycation end products (AGEs), whose receptors are on monocytes, endothelial cells and macrophages, which secrete interleukin 1β (IL-1β), interleukin 6 (IL-6), Prostaglandin E2 (PGE2) and tumor necrosis factor alpha (TNF-α)." (PMID 40141192, 2025). "It was hypothesized that proinflammatory cytokines from GCF or systemic circulation, such as TNF-α, IL-1β, and IL-6, induce hyperlipidemia due to enhanced hepatic lipogenesis, increased synthesis of triglycerides, and reduced clearance of both triglycerides and LDL." (PMID 36983201, 2023). "Moreover, hyperlipidemia–induced dysbiosis can lead to disorder of the local immune system, accompanied by production of inflammatory cytokines such as IL–1β, IL–6, and tumor necrosis factor (TNF)–α, and adipokines such as leptin in addition to increasing the intestinal permeability." (PMID 36364184, 2022). "We aimed to characterize variability in postprandial inflammatory responses using traditional (IL-6) and novel [glycoprotein acetylation (GlycA)] biomarkers of inflammation and dissect their biological determinants with a focus on postprandial glycemia and lipemia." (PMID 34100082, 2021). "In studies with sea buckthorn berry extract, the polyphenols significantly reduced serum levels of TNF-α and IL-6 and also alleviated vascular impairment by decreasing the expression of eNOS and ICAM-1 in the aortas of rats with hyperlipidemia." (PMID 41156509, 2025). "Stimulated macrophages reportedly release IL-6 and MCP-1, which induce inflammation and interfere with carbohydrate and lipid metabolism, leading to hepatocyte hyperlipidemia." (PMID 41462942, 2025). "Hyperlipidemia can potentially instigate enduring inflammation in the body, promoting the secretion of inflammatory agents like tumor necrosis factor-α (TNF-α) and interleukin-6 (IL-6)." (PMID 38831342, 2024). "Together, these data suggest CD146/Gp130 interaction blocks the IL‐6‐induced STAT3 signaling activation and promotes the pro‐inflammatory polarization of ATMs under hyperlipidemia conditions." (PMID 35258174, 2022). "Under hyperlipidemia conditions, CD146 interacts with Gp130 to inhibit ACM (mainly IL‐6)‐induced STAT3 activation." (PMID 35258174, 2022). "Hyperlipidemia resulted in higher serum concentrations of TNF-α and IL-6, but LHD and atorvastatin treatment significantly reduced the expression of inflammatory factors." (PMID 34881240, 2021). "The results from the PPI analysis showed that the targets for YCWL relating to the treatment of hyperlipidemia mainly involved AKT1, IL6, VEGFA, and PTGS2." (PMID 34746316, 2021). "In conclusion, the effect of SP-FJG in regulating glucose tolerance, TNF-α, IL-6, FINS, and hyperlipidemia was better than using SP individually in ZDF rats." (PMID 32351607, 2020). "Besides oxLDL stimulation, we harvested the HFD‐fed mouse serum including hyperlipidemia to treat MPMs and found that WEE1 deletion inhibited hyperlipidemia‐induced TNF‐α and IL‐6 levels in cultured MPMs." (PMID 40202104, 2025).
hyperlipidemia (continued). "After drug administration, ATO and BA significantly reduced IL-6 and TNF-α levels (p < 0.01), suggesting that BA could alleviate systemic inflammation during hyperlipidemia development." (PMID 40529499, 2025). "In case of liver inflammation related genes (IL-1β, TNF-α, IL-6, IL-18, CCL20, and NF-κB) their expression levels were significantly (P < 0.05) upregulated and IL-1RN was significantly (P < 0.05) downregulated in the liver of hyperlipidemia group." (PMID 41144456, 2025). "In our study both moderate- and high-intensity statin therapies could significantly reduce the hs-CRP and IL-6 levels in patients with T2DM and mild hyperlipidemia." (PMID 38310429, 2023). "HFD induces hyperlipidemia proven by increased plasma concentration of CT, LDL-C, and TG, which initiates an inflammatory response, supported through increased inflammatory biomarkers (hs-PCR, TNF-α, IL-1β, IL-6) compared to the BD group." (PMID 35204113, 2022). "Oral administration of SVP in T2DM mice also could improve the diabetic complications of hyperlipidemia and inflammation response, indicating as lower concentrations of TC, TG, LDL-c, FFA, TBA, TNF-α, IL-6, and higher levels of IL-10 in serum." (PMID 36337615, 2022). "In addition, inflammatory molecules and apoptosis-related proteins, such as IL-6, TNF-α, and BAX, were abnormally elevated in patients with hyperlipidemia." (PMID 34307504, 2021). "MG induced Nrf2/HO-1 signaling, diminished Tylo-induced hyperlipidemia, oxidative stress, IL-1β as well as TNF-α and IL-6 that might arise from the suppression of NLRP3 inflammasome." (PMID 32992548, 2020). "Furthermore, the expression levels of the inflammatory transcription factors, tumor necrosis factor-α and interleukin-6, were shown to be reduced in the XZK group when compared with the hyperlipidemia group." (PMID 25371725, 2014). "In addition, GLXB treatment could also reduce the levels of IL6 and TNF-α in the serum of hyperlipidemia rats." (PMID 36120369, 2022). "In our study, the HLD induced hyperlipidemia, which is highlighted by higher serum levels of TC, LDL-C, and initiated an inflammatory process shown by higher serum levels of inflammation markers (hs-PCR, TNF-α, IL-1β, IL-6) in the HLD group compared to the group fed with SD." (PMID 34300308, 2021). "In addition, SREBP decoy ODN decreased AST, ALT, total cholesterol, and triglyceride levels in the serum of hyperlipidemic mice fed with HFD, and furthermore, significantly inhibited the pro-inflammatory cytokine expressions of IL-6, TNF-α, IL-1β, and IL-8 in HFD-induced hyperlipidemia mouse models." (PMID 31952262, 2020). "We found a negative correlation between TAS and hyperlipidemia, IL-6, and IL-8." (PMID 27994711, 2016). "Oral infection with P. gingivalis induced a significant elevation in serum IL-6 levels during short-term infection, regardless of whether hyperlipidemia was present." (PMID 21625524, 2011). "Moreover, HLF could significantly reduce the levels of NLRP3, caspase-1, IL-1β, IL-6, IL-18, and TNF-α and increase the activities of plasma SOD, CAT, and GSH-PX, which suggested that HLF could effectively relieve the inflammatory response and oxidative stress induced by hyperlipidemia." (PMID 36425260, 2022).